CRP (C-reactive protein)
Diseases named in the same sentence as CRP in open-access papers (continued):
Sharing a sentence is not in itself a finding about the gene and the disease.
cancer (continued). "Another study found that elevated CRP levels may indicate aggressive cancer progression and potential resistance to therapy with the ICI atezolizumab in combination with bevacizumab." (PMID 41306979, 2025). "Interestingly, CRP exhibits dual roles in tumor biology, potentially promoting or inhibiting cancer cell killing." (PMID 40420174, 2025). "CRP is a general inflammatory marker that can be elevated in various conditions, including cancer." (PMID 40791284, 2025). "It should be noted that CRP is likely not the cause of cancer itself, but rather a response marker of environmental risk factors." (PMID 40141426, 2025). "In this context, inflammation emerges as a pivotal oncogenic mechanism, with biomarkers such as IL-6, TNF-α, C-reactive protein (CRP), erythrocyte sedimentation rate (ESR), and fibrinogen representing clinically relevant indicators for integrative cancer risk assessment." (PMID 41301215, 2025). "Although limited data specific to cancer exists, it was recently shown that CRP could directly bind integrin α2 and FcγRI in breast cancer to promote proliferation, adhesion, and invasion in cancer cells both in vitro and in vivo." (PMID 41614767, 2025). "Therefore, CRP as an important indicator of inflammation is closely related to the psychological factors of patients with cancer." (PMID 40966684, 2025). "Although a higher CRP has been associated with poor outcomes in multiple cancer types, including NET in some but not all studies, evidence for ESR is scarce, and the association between ESR and OS in patients treated with PRRT has not been studied previously." (PMID 38477040, 2025). "As for the mechanism underlying those findings, CRP and NLR levels may reflect the tumor‐promoting inflammatory microenvironment and immune system balance in malignant tumors." (PMID 41423968, 2025). "This distinction could explain why certain biomarkers (e.g., CRP or NLR) show varying prognostic values across cancer types." (PMID 41267986, 2025). "Additional analysis indicates several key pro-tumorigenic processes may also be altered by CRP PPIs as determined through the Hallmarks of Cancer dataset." (PMID 41614767, 2025). "Several inflammatory markers, including CRP, have been studied in the context of cancer." (PMID 39870769, 2025). "Also, certain markers of inflammation (e.g., CRP, IL-6) are elevated in chronic diseases, such as cancer, and have a relationship with poor mental health." (PMID 40566289, 2025). "This multicenter cohort study aimed to evaluate the prognostic value of a novel inflammatory score, derived from baseline white blood cell (WBC) count and C-reactive protein (CRP) z-scores, in predicting survival outcomes and nutritional deterioration among cancer patients." (PMID 40832638, 2025). "Further, these and other signaling mechanisms identified (e.g., TGFβ signaling, EMT) may also broaden the role of CRP in regulating processes critical to neoplastic development, metastasis, recurrence, and treatment resistance in cancer." (PMID 41614767, 2025). "CRP, WBC count, total cholesterol, and LDL cholesterol significantly mediated the association between brisk walking pace and any cancer, with proportions of mediation being 6.4% (95% CI 4.4–8.7%), 11.4% (8.4–17.1%), 9.3% (7.1–12.9%), and 8.3% (6.1–11.9%), respectively." (PMID 40275681, 2025). "Furthermore, systemic inflammatory markers, including C-reactive protein (CRP) and the neutrophil-to-lymphocyte ratio (NLR), have been associated with worse cancer-specific survival in EC." (PMID 40805172, 2025). "The lower CRP concentrations observed in this review are potentially clinically meaningful, as these concentrations are associated with a decreased risk of chronic diseases, including CVD, cancer, and all-cause mortality." (PMID 40043850, 2025).
cancer (continued). "On the other side, patients with PE as the first manifestation of cancer had the most pronounced inflammatory response with the highest CRP serum levels which might be a result of the combination of the more severe PE at presentation and advanced tumor nature." (PMID 40276977, 2025). "CRP trajectories have been shown to play an important role in cancer occurrence." (PMID 41409302, 2025). "Indeed, in all three subgroups of cancer patients, the dietary intervention was accompanied by a significant reduction in CRP levels." (PMID 41409302, 2025). "This could be complemented by verifying the basal proteomic landscape of CRP PPIs across cancers and in stromal cell types." (PMID 41614767, 2025). "There are reports suggesting that higher levels of CRP may be related not only to CVD and all-cause mortality but also to higher odds of death due to cancer, which is a very common cause of death in PWH." (PMID 40006998, 2025). "To further explore systemic inflammation, we compared CRP levels across our cancer cohorts." (PMID 40506552, 2025). "The concept of a composite inflammatory-nutritional index is not entirely novel; the prognostic nutritional index and the CRP/albumin ratio have both been linked to cancer outcomes in cardiac and non-cardiac settings." (PMID 41473193, 2025). "Moreover, the circulating levels of inflammation biomarkers [e.g., C-reactive protein (CRP) and white blood cell (WBC) count] were positively associated with cancer and CVD mortality." (PMID 40023976, 2025). "After adjusting for potential confounders, CRP, WBC count, total cholesterol, and LDL cholesterol showed statistically significant partial mediating effects on the association between walking speed and any cancer in the UK Biobank." (PMID 40275681, 2025). "Plasma CRP and soluble urokinase plasminogen activator receptor (suPAR), which indicates inflammatory activity, demonstrated significant correlations with newly diagnosed cancer during follow-up after adjusting for age and sex." (PMID 39980561, 2025). "It is important to point out that patients with cancer often present with increased levels of both inflammatory parameters (especially CRP), reflecting cancer-related inflammation, and hemostatic biomarkers (eg, fibrinogen, D-dimer, FVIII activity), indicating cancer-induced hypercoagulability." (PMID 40524734, 2025). "C-reactive protein (CRP), a well-established systemic inflammatory marker, is strongly associated with tumor CRC progression and recurrence risk, reflecting the inflammatory microenvironment that fosters cancer development and metastasis." (PMID 41517322, 2025). "Serum albumin, although affected by factors beyond nutrition, remains a widely used marker associated with prognosis and perioperative risk, while C-reactive protein (CRP) and composite indices incorporating CRP and albumin are used to evaluate the inflammatory component of cancer cachexia." (PMID 41463399, 2025). "At the clinical level, previous meta-analyses have provided preliminary evidence that exercise can improve common metabolic disturbances in cancer patients, including blood glucose, insulin, and triglycerides, as well as inflammatory markers such as IL-6, C-reactive protein (CRP), and TNF-α." (PMID 40895542, 2025). "Nevertheless, the CRP level is also elevated in almost all malignant neoplasms." (PMID 40125102, 2025). "Elevated CRP levels within the inflammatory and tumor microenvironment promote various cancers." (PMID 39267838, 2024). "In the present study, 32 patients (32%) met the criteria of low Alb (Alb < 3.3 g/dL) and high CRP (CRP > 1.9 mg/dL) levels, and approximately half of them experienced cancer-related death within 3 months of starting treatment, with 70% succumbing to cancer within 7 months." (PMID 38592548, 2024).
cancer (continued). "Serum CRP can cause systemic inflammation by secreting various pro-inflammatory cytokines, such as IL-1, IL-6 and TNF-α, resulting in the gradual loss of important protein components in host, leading to the death of cancer patients." (PMID 38184747, 2024). "In contrast, CRP levels were significantly higher in cancer patients than in controls." (PMID 39619813, 2024). "In patients with cancer, CRP levels in the circulatory system are elevated." (PMID 38273418, 2024). "In conclusion, we show that measuring CRP in urine is a feasible analytical method, and that uCRP could potentially be a promising biomarker in various diseases including other cancer types." (PMID 39309742, 2024). "Cancer treatment led to a significant reduction in CRP levels." (PMID 39619813, 2024). "The most famous marker in inflammation, with a certain contribution to cancer development, is CRP." (PMID 39452544, 2024). "Various inflammatory markers, including neutrophil-to-lymphocyte ratio (NLR), monocyte-to-lymphocyte ratio (MLR), platelet-to-lymphocyte ratio (PLR), and C-reactive protein-to-albumin ratio (CAR), have been linked to the effectiveness of immunotherapy in multiple types of malignancies." (PMID 39132507, 2024). "CRP could alter the expression of proto-oncogenes and inhibitory genes through different pathways, facilitating cancer cell proliferation, migration, invasion, and chemotherapy resistance." (PMID 39010859, 2024). "Furthermore, several studies have demonstrated that PCa patients exhibiting elevated CRP levels tend to have poorer OS, cancer-specific survival (CSS), and progression-free survival (PFS)." (PMID 39267848, 2024). "There was a significant correlation between the CRP IHC score in cancer tissues and its serum level, suggesting that the interaction of CRP with CD64‐expressing macrophages in the tumor microenvironment may play a critical role in ccRCC tumor progression." (PMID 39564003, 2024). "The direct comparison of diagnostic accuracies between PCT and CRP within our study provides insights into the relative performance of these two biomarkers in non-neutropenic cancer patients." (PMID 38438974, 2024). "An increase in CRP level with a decrease in Albumin level has been found in many cancers." (PMID 38903332, 2024). "Given the data showing that systemic inflammation takes part in tumor development and progression, CRP, which is an acute-phase protein, may serve as a biomarker for predicting outcomes in cancer patients." (PMID 39272712, 2024). "Our findings in OC confirmed the prognostic value of CRP for additional cancers." (PMID 38172843, 2024). "The detailed mechanistic roles of CRP in cancer are still being unravelled." (PMID 39309742, 2024). "Similarly, Calapai and co-workers investigated the ability of immune biomarkers, such as CRP, to forecast the severity of pain in cancer patients." (PMID 39199993, 2024). "Even so, the consistency of the findings allows us to consider the study sufficient to support the proposition of additional studies, such as a clinical trial to test an antibiotic therapy strategy based on the behavior of CRP in cancer patients hospitalized with acute bacterial infection." (PMID 39272020, 2024). "Cancer patients treated with DOXO experienced high levels of CRP, erythrocyte sedimentation rate, IL-6, and IL-1β that may contribute to additional complications, including organ dysfunction or failure." (PMID 38818214, 2024). "Similarly, the Washington consensus statement identified CAR components CRP (>5 mg/L) and albumin (<3.2 g/dL) as biochemical indicators of cancer-cachexia." (PMID 38975012, 2024). "IL6 inhibitors have been shown to prevent the conversion of non-stem cancer cells to cancer stem cells and alleviate cancer-associated anemia by increasing hemoglobin and reducing CRP levels." (PMID 39766086, 2024).
cancer (continued). "Notably, CysC demonstrated the highest predictive efficacy across all mortality outcomes, followed by eGFR, while urea nitrogen, creatinine, uric acid, and CRP exhibited relatively lower predictive performance for all-cause, CVD, and cancer mortality." (PMID 38597157, 2024). "Serum CRP and albumin are two crucial acute-phase proteins that reflect the nutritional status during the systemic inflammatory response, which commonly occurs in malignant tumors." (PMID 38903332, 2024). "The CRP could increase dramatically within 24–72 h of severe tissue damage such as trauma and progressive cancer." (PMID 39075344, 2024). "Additionally, the related influencing factors for patients with normal serum iron are found to be CRP, albumin, total cholesterol, and cancer staging." (PMID 38562035, 2024). "For instance, elevated CRP levels have been associated with cancer risk in both ESRD and non-ESRD populations, reinforcing the idea that chronic inflammation is a critical factor in malignancy development." (PMID 39712803, 2024). "Hematological parameters (complete blood count, liver function test, kidney function test, C-reactive protein), cancer markers (carcinoembryonic antigen, lactate dehydrogenase), and mental health indices (quality of life, survival rate) also showed significant improvement." (PMID 39246981, 2024). "CRP-level findings can also be utilized for operated malignancy patients' follow-up regarding recurrence or in pre-malignant cases that might have undergone malignant transformation." (PMID 38910781, 2024). "After it was understood that the immune and nutritional status had an effect on cancer prognosis, various parameters and indices reflecting the immune status (CRP, lymphocyte, albumin, neutrophil, NLR, PLR, MLR, pan-immune ınflammatıon value (PIV)) have been the subject of studies." (PMID 38777931, 2024). "To evaluate predictors and their association with overall survival from the start of last-line chemotherapy until death, we explored models within PAN and GI groups based on baseline PS, albumin, CRP, and mGPS in a basic model (adjustments for age, sex, hospital size, and cancer diagnosis)." (PMID 39330032, 2024). "This tool is based on the CRP and albumin levels at the time of diagnosis of advanced cancer." (PMID 39330032, 2024). "The lymphocyte count-to-CRP ratio (LCR) has been associated with symptom severity in patients with coronavirus disease 2019 and exhibits predictive value for various clinical conditions, including cancer and myocardial infarction." (PMID 39685802, 2024). "Therefore, some studies used the combination of CRP and albumin to predict the prognosis of cancer patients." (PMID 38803531, 2024). "Thus, CRP serves not only as a biomarker for cancer but also as a potential link between chronic inflammation and cancer progression." (PMID 38474160, 2024). "However, a CRP level of 5 mg/dL in patients with advanced cancer was considered to be effective in the screening of patients and their family caregivers at risk for negative impacts of cancer cachexia." (PMID 39765960, 2024). "We hypothesize that cancer patients with a good response to antibiotic therapy show a faster decline in serum CRP levels, which would allow us to identify candidates for short-course treatments." (PMID 39272020, 2024). "Systemic inflammatory responses, including changes in biomarkers such as C-reactive protein (CRP), neutrophil-to-lymphocyte ratio (NLR), and platelet-to-lymphocyte ratio (PLR), have been shown to be closely linked with the prognosis of various cancer types." (PMID 39592977, 2024). "CRP is a mediator and indicator of inflammatory processes, including those in patients with cancer." (PMID 39771527, 2024). "A serum CRP value of 5 mg/dL may be one indicator used to initiate multimodal care for cancer cachexia." (PMID 39765960, 2024).
cancer (continued). "Elevated levels of blood CRP (bCRP) have been associated with an increased risk of cardiovascular disease but also with increased risk of cancer in the general population, including non-sigmoid colon and lung cancers, breast, ovarian and liver cancers." (PMID 39309742, 2024). "This phenomenon of poor survival in populations with low PK of antibody drugs has been reported repeatedly, suggesting that antibody concentrations are low in patients with impaired conditions, including cancer cachexia, characterized by poor PS, low Alb level, and high CRP level." (PMID 39091595, 2024). "We hypothesized that IL-6 would be a more sensitive marker than CRP in the prognostication of cancer cachexia." (PMID 38539528, 2024). "The predictive ability for patients with advanced cancers might be improved by combining CRP with other parameters, such as plasma albumin and NLR." (PMID 37009523, 2023). "However, CRP measurement has now been incorporated into national UK guidance for minimum datasets in patients with cancer." (PMID 36207803, 2023). "Elevated CRP levels are strong indicators of poor prognosis in cancer treatment." (PMID 39554800, 2023). "While IMDC shares some features in common with IBD, IMDC is still a distinct entity, which may explain the observation of our study that CRP level is less informative in the context of more confounding factors present in a population of patients with cancer." (PMID 37476185, 2023). "As is well known, elevated CRP levels are a useful indicator of the development of selected human diseases, including bacterial and fungal infections, cardiovascular diseases (hsCRP), autoimmune diseases, and cancer." (PMID 38136377, 2023). "Hence, CRP assessment has helped in increasing success in cancer survival and mitigation of worsening exacerbation or recrudescence of the disease." (PMID 39554800, 2023). "Moreover, our data revealed that serum CRP concentration correlated with the presence of lymph node and distant metastases, advanced cancer stage and gastric wall invasion, while IL-6, CEA and CA 19-9 levels correlated with nodal involvement." (PMID 37240178, 2023). "Human cross-sectional studies support that regular moderate physical exercise releases anti-inflammatory cytokines and reduces the production of pro-inflammatory cytokines or cancer biomarkers, such as tumor necrosis factor-alpha (TNFα), interleukin-6 (IL-6), and C-reactive protein (CRP)." (PMID 36765772, 2023). "The prognostic role of the CRP level has also been assessed in combination with the albumin level in the mGPS, an inflammatory/nutritional index, which is the most validated prognostic index in patients with cancer." (PMID 36831431, 2023). "The relationship between CRP and cancer may occur with some biological mechanisms including tissue inflammation secondary to tumor growth and immune response to tumor antigens." (PMID 36793395, 2023). "Dietary interventions may help to decrease chronic inflammation by decreasing inflammatory biomarkers such as CRP, IL6 that are associated with fatigue in cancer patients." (PMID 36839371, 2023). "Despite the lack of substantial evidence to support this, CRP has been linked to the question of cancer causation for many years." (PMID 39554800, 2023). "Recent studies on specific cancer types (urothelial carcinoma and non-small cell lung cancer) showed that CRP kinetics could predict the response to immunotherapy." (PMID 37626775, 2023). "In COVID-positive cancer patients, CRP levels may be especially useful in prognosis, as they have been shown to be significantly correlated with higher odds of COVID-related mortality." (PMID 38127882, 2023). "CRP is an acute-phase reactant that is mainly produced by hepatocytes under the influence of proinflammatory cytokines, particularly interleukin-6 (IL-6), which are commonly over-produced in cancer cells and immune cells that infiltrate tumor tissue." (PMID 37509622, 2023).